TCF7L2 (transcription factor 7 like 2)
Diseases named in the same sentence as TCF7L2 in open-access papers (continued):
Sharing a sentence is not in itself a finding about the gene and the disease.
diabetes (continued). "Except for TCF7L2, most SNPs identified so far displayed weak or modest effects on diabetes." (PMID 24653947, 2011). "TCF7L2 therefore appears as a genetic link between diabetes and atherosclerosis." (PMID 21423583, 2011). "Third, as diabetes and fasting glucose values are plausibly intermediate variables between TCF7L2 and retinal phenotypes, our analyses conditional on diabetes/fasting glucose values need to be interpreted with caution as this method may introduce confounding." (PMID 20478041, 2010). "We aimed to characterise the possible longitudinal associations of common diabetes-susceptibility variants in the KCNJ11, PPARG, TCF7L2, IGF2BP2, CDKAL1, SLC30A8 and HHEX gene loci, with fasting glucose level; and of an obesity-associated variant in the FTO gene, with body mass index (BMI)." (PMID 20929593, 2010). "Our data also suggests that co-existence of TCF7L2 variants and the SPINK1 and CTSB mutations, that predict susceptibility to exocrine damage, may interact to determine the onset of diabetes in TCP patients." (PMID 18706099, 2008). "We hypothesized that we would observe an association of variants in the TCF7L2 gene with FCPD, if diabetes in these patients is T2D." (PMID 18706099, 2008). "Ambiguous matches were found in TCF7 and TCF7L2, the later, a gene recently linked to the development of diabetes (but not DN)." (PMID 18698414, 2008). "With the exception of CDK5 and TCF7L2, no other gene variant showed significant association with any diabetes-related quantitative traits." (PMID 18598350, 2008). "We use FHS 100K SNPs in an in silico replication analysis that tests the hypothesis that SNPs in LD with published causal variants in PPARG, ABCC8, TCF7L2, CAPN10, and HNFa are associated with diabetes and related quantitative traits." (PMID 17903298, 2007). "Therefore, TCF7L2 could be a promising regulator of the NAFLD associated with high-carbohydrate diets and diabetes since TCF7L2 deficiency may lead to development of NAFLD by promoting utilisation of excess glucose pools through activating DNL." (PMID 36759348, 2023). "There are, however, some data from the Finnish Diabetes Prevention Study (FDPS) and the Diabetes Prevention Program (DPP) studies that suggest that lifestyle intervention may overcome the increased risk of some genetic polymorphisms, e.g., TCF7L2 and PPARγ2 genes." (PMID 37049626, 2023). "Moreover, TCF7L2 may independently influence cancer of patients with diabetes, as the TCF7L2 gene is a key component of the Wnt/b-catenin signal pathway and exerts a vial part in the regulation of cell development and growth." (PMID 27738320, 2016). "Indeed, TCF7L2 was once described as the biggest story in diabetes since HLA." (PMID 26937418, 2015). "This may relate to sample size, and/or to the observation across several studies that TCF7L2 variants are associated with reduced BMI in diabetes cases (but not in controls)." (PMID 26937418, 2015). "However, we report an association between the TCF7L2 rs7903146 polymorphism and focal arteriolar narrowing in Caucasians with hypertension or without diabetes." (PMID 20478041, 2010). "However, our study is the first to report an association between the TCF7L2 rs7903146 polymorphism and focal arteriolar narrowing in Caucasians with hypertension or without diabetes." (PMID 20478041, 2010). "It is possible that the TCF7L2 rs7903146 variant may be related to focal arteriolar narrowing not through its effect on diabetes but through other, retinal-specific mechanisms (i.e. pleiotropic effects)." (PMID 20478041, 2010). "Since, TCF7L2 is a major susceptibility gene for T2D, it may be hypothesized that the diabetes in TCP patients may not be similar to T2D." (PMID 18706099, 2008). "However, co-inheritance of the TCF7L2 variants with the pancreatitis associated susceptibility variants in SPINK1 and CTSB genes may predict the development of diabetes in these patients, but these observations need to be confirmed independently." (PMID 18706099, 2008).
diabetes (continued). "We next examined whether the characteristics of those with diabetes varied by TCF7L2 status." (PMID 17181866, 2006). "The improved lipid profile was present even in the population without diabetes or IFG (in whom a smaller waist circumference was also found) and therefore this finding is unlikely to be an artifact of TCF7L2 polymorphism carriers developing diabetes at lower levels of abdominal obesity." (PMID 17181866, 2006). "In addition, because individuals with single autoantibodies have a lower risk of developing T1D with respect to those with multiple autoantibodies, it is possible that these subjects, in the absence of this TCF7L2 variant, may not develop overt diabetes." (PMID 33810109, 2021). "We investigated if red meat consumption increases the risk of latent autoimmune diabetes in adults (LADA) and T2D, and potential interaction with family history of diabetes (FHD), HLA and TCF7L2 genotypes." (PMID 32444887, 2021). "It should further be noticed that genes of importance for islet function and diabetes such as PDX1, TCF7L2, FOXA2, FOXO1, NEUROD1 and BACH2 have C1, C3 or both these sites at their ATAC-seq open chromatin regions." (PMID 31123324, 2019). "Interestingly, here we find decreased expression in parallel with increased DNA methylation of several candidate genes for T2D, such as TCF7L2 and GLIS3, in palmitate-treated human islets, suggesting that lipid-induced epigenetic modifications may affect the risk for diabetes." (PMID 24953961, 2014). "First, as already shown by us for TCF7L2 and GCKR, a role of CACNA1E in determining beta cell function can be detected also in overt diabetes." (PMID 22427875, 2012). "Despite the importance of beta cell function to the development of diabetes, less attention has been given to the expression of these genes in human pancreatic islets (with the exceptions of KCNJ11 and TCF7L2) due to the lesser availability of this tissue." (PMID 20548773, 2010). "We identify an interaction between a TCF7L2 intronic SNP and PGS SNPs altering sites bound by the KDM2A TF for glycated haemoglobin (HbA1c) levels, a biomarker of blood glucose widely used in the diagnosis and management of diabetes." (PMID 41332835, 2025). "The existence of TCF7L2, as one of the miR-105 target genes, within the analyzed data, supports the idea of diabetes as one disease regardless of the type." (PMID 41376825, 2025). "The direct Wnt/β‐catenin signalling target genes, such as transcription factor 7 like 2 (TCF7L2), wnt1‐induced secreted protein 1 (WISP1), GLP1 and peroxisome proliferator‐activated receptor delta (PPARδ), play major roles in obesity and diabetes." (PMID 35384342, 2022). "Furthermore, several genes involved in the endocrine specification and diabetes development were significantly downregulated, such as HES1, INSM1, HNF1A, NEUROD1, NGN3, NKX2.2, GIPR, MNX1, PROX1, TCF7L2, and HHEX." (PMID 33473118, 2021). "While TCF7L2 isoforms are not significantly altered in T2D, both HNF-1α and GCK diabetes associated alleles result in alternative splicing variation, and isoforms of HNF-1α are associated with differential efficiency in insulin gene regulation." (PMID 33088281, 2020). "In this study, our purpose was to investigate the association between rs7903146 in TCF7L2 and CGM derived measures in a cohort of middle-aged participants without diabetes." (PMID 26914832, 2016). "The exact mechanisms of TCF7L2 in the development of diabetes have not been fully determined but it is suggested that diabetes arises as a consequence of reduced pancreatic islet mass and/or impaired function." (PMID 27058589, 2016). "The associations of 23 SNPs located within 17 candidate genes (MTHFR, PPARγ, LPL, INSIG, TCF7L2, FTO, KCNJ11, JAZF1, CDKN2A/B, ADIPOQ, WFS1, CDKAL1, IGF2BP2, KCNQ1, MTNR1B, IRS1, ACE) with overweight and obesity, diabetes, metabolic phenotypes, and MetS were examined in both studies." (PMID 24959828, 2014).
diabetes (continued). "In subjects without known diabetes (n=961) recruited from the Chennai Urban Rural Epidemiology Study (CURES), OGTT, IDRS, and genotyping of rs12255372 (G/T) and rs7903146(C/T) of TCF7L2 polymorphisms were done." (PMID 21441683, 2011). "In addition, T2D and pre-diabetes groups exhibited significantly higher expression of TCF7L2 than the non-disease group in visceral adipose tissue of Asian Indians." (PMID 40050721, 2025). "In particular, we investigated whether the association between TCF7L2 polymorphisms and angiographically characterized CAD differs between patients with diabetes and non-diabetic individuals." (PMID 21423583, 2011). "After adjusting for diabetes duration the odds ratio did not change (OR = 1.57) and the P-value reduced just minimally (from P = 0.046 to P = 0.057), thus indicating independent effect of the TCF7L2 genotype." (PMID 21349175, 2011). "There are no published reports on whether the biological effects of TCF7L2 gene on diabetes are partly via inflammation or whether inflammation alters the effects of TCF7L2 on insulin secretion and other metabolic traits." (PMID 19825152, 2009). "Thus, we aimed to study the association between the rs7903146 polymorphism, the most widely studied TCF7L2 genetic marker, and CVD in individuals with and without diabetes." (PMID 19924244, 2009). "Thus, although the variations in TCF7L2 increase the risk for T2D and may affect insulin secretion, they do not alter susceptibility to FCPD, the diabetes in TCP patients." (PMID 18706099, 2008). "A more recent study on genome-wide DNA methylation of pancreatic islets showed that DNA methylation patterns of T2D candidate genes, including the TCF7L2, FTO and HHEX, were altered in human islets from patients with T2D compared to controls without diabetes." (PMID 28067832, 2017). "In the Diabetes Prevention Program (DPP) study, the authors did not detect significant interactions between genotypes at either SNP (TCF7L2 rs7903146 and rs12255372, SLC30A8 rs13266634) and the interventions." (PMID 23997649, 2013).
Obesity (109 papers, 2006 to 2026). Accumulation of substantial excess body fat. "For example, the susceptibility to obesity and T2DM is higher among people carrying genetic mutations of genes such as FTO (fat mass and obesity‐associated gene) or TCF7L2 (transcription factor 7‐like 2) if exposed to a high‐carbohydrate or high‐fat diet." (PMID 41567168, 2026). "The interactions between the FTO (Fat Mass and Obesity‐Associated Gene), TCF7L2 (Transcription Factor 7‐Like 2), and APOE (Apolipoprotein E) genes and nutrients play a crucial role in the metabolic pathways that determine disease risk." (PMID 41567168, 2026). "Several studies suggested that the FTO and TCF7L2 variants were the most robust genetic predictors for obesity and T2D in SA, respectively which is similar to the findings in European research." (PMID 39283705, 2025). "The risk of T2D conferred by the TCF7L2 rs7903146 variant was reportedly independent from BMI and obesity." (PMID 36674502, 2023). "The TT genotype of TCF7L2 rs7903146 showed a significantly increased risk for obesity (OR = 2.76, 95% CI 1.38–5.50, p = 0.003)." (PMID 35292917, 2022). "Obesity was associated with reduced TCF7L2 transcript levels in whole subcutaneous abdominal AT but paradoxically increased expression in adipose progenitor cells." (PMID 36532520, 2022). "Although the TCF7L2 encodes the main effector involved in this signaling pathway, few studies investigate the association between the rs7903146 and risk for obesity." (PMID 33996288, 2021). "Nevertheless, additional studies are needed to understand the TCF7L2 rs7903146 association with obesity and with BMI variation in different age groups of populations across the world." (PMID 33996288, 2021). "Seven single nucleotide polymorphisms (SNPs) from the Transcription factor 7-like 2 and fat mass and obesity-associated genes were used to construct two metabolic genetic risk scores (GRS): 7-SNP and 3-SNP GRSs." (PMID 34578944, 2021). "In this study, it was quoted that obesity status should be taken into consideration when classifying patients to obtain more accurate information about an interaction between diet and TCF7L2 rs7903146 variant for T2DM risk." (PMID 31581435, 2019). "A study found that susceptibility gene TCF7L2 conferred an increased risk of BD in the presence of elevated BMI, suggesting an interaction between an interaction between obesity and BD risk." (PMID 30761021, 2019). "The direct association of TCF7L2 with obesity is unclear; however, it is well-established that TCF7L2 is expressed in adipose tissue and involved in Wnt/β-catenin signaling dependent regulation of adipogenesis." (PMID 30065654, 2018). "Strong association between the MC4R gene and risk of obesity was identified by a genome-wide association (GWAS) study whereas the association between the Transcription Factor 7-Like 2 (TCF7L2) gene and risk of T2D was identified by a genome wide linkage study." (PMID 29182660, 2017). "Our study provides first-time insight into the role of the TCF7L2 rs7903146 (C/T) gene polymorphism in obesity among Cameroonians." (PMID 28420445, 2017). "This study aimed at investigating the association between the rs7903146 (C/T) polymorphism of the TCF7L2 gene with obesity in a Cameroonian population." (PMID 28420445, 2017). "Obesity significantly interacted with the TCF7L2-rs7903146 on T2D prevalence, associations being greater in non-obese subjects." (PMID 27929407, 2016). "In conclusion, we have comprehensively demonstrated that the TCF7L2-rs7903146 polymorphism interacts with obesity status in determining T2D risk, emphasizing the heterogeneity of genetic variants’ T2D risk prediction." (PMID 27929407, 2016). "Combining longitudinal and cross-sectional analyses in a well-characterized population, we have obtained new epidemiological evidence to unravel the complex relationship between the TCF7L2-rs7903146 polymorphism, obesity, and T2D." (PMID 27929407, 2016).
Obesity (continued). "According to our results, in studies aimed at analyzing gene–diet interactions involving the TCF7L2 polymorphism in the determination of T2D, stratification by obesity status should be needed." (PMID 27929407, 2016). "Bearing the results of the result in EPIC cohort in mind, this interaction, therefore, must be prospectively validated in studies focusing on the TCF7L2-rs7903146 polymorphism (to avoid the need of correction for multiple SNP comparisons) and obesity." (PMID 27929407, 2016). "That is the case of the FTO (fat mass and obesity associated) gene and its association with obesity and related traits or the TCF7L2 gene and its association with T2DM." (PMID 26927084, 2016). "We comprehensively investigated gene-obesity interactions between the TCF7L2-rs7903146 C > T polymorphism on T2D (prevalence and incidence) and analyzed other T2D-polymorphisms in a sub-sample." (PMID 27929407, 2016). "In terms of obesity as an outcome, our results also suggest an inverse association of the TCF7L2 polymorphism with BMI in T2D subjects." (PMID 27929407, 2016). "The association between TCF7L2 and obesity in Cameroon was determined by comparing the allele and genotype frequencies of rs12255372 (G/T) in the 35 obese patients and 30 healthy controls." (PMID 26608632, 2015). "The aim of this study therefore was to assess the possible association of the TCF7L2 rs12255372 polymorphism with obesity and weight-related traits in a Cameroonian population." (PMID 26608632, 2015). "The aim of this study was to assess the possible association of the TCF7L2 rs12255372 polymorphism with obesity and weight-related traits in a Cameroonian population." (PMID 26608632, 2015). "The aim of this study was to assess the association between the transcription factor 7-like 2 (TCF7L2) gene polymorphism (rs12255372 G/T) and obesity and weight-related traitsin a Cameroonian population." (PMID 26608632, 2015). "Of these core SNPs, 11 in FTO, TSPAN8, and TCF7L2 have been reported to be associated with T2D, obesity, or both, providing an independent replication of previously reported SNPs." (PMID 23626757, 2013). "One possible explanation by Cauchi and collegues is that the risk for T2DM related to TCF7L2 seems to be modulated by the obesity status of an individual with stronger effects in the obese." (PMID 20092643, 2010). "As second strongest signal, we found association between the T2DM susceptibility gene TCF7L2 risk allele and obesity related traits in patients with PCOS." (PMID 20092643, 2010). "Genetic factors implicated in treatment variability include variants in GLP-1 receptor, GIP receptor, β-arrestin 1, transcription factor 7-like 2, fat mass and obesity-associated protein, and melanocortin 4 receptor, although tirzepatide-specific validation remains limited." (PMID 42198465, 2026). "Furthermore, LADA exhibits a strong association with the T2DM-associated variant transcription factor 7-like 2 (TCF7L2), particularly in cases involving obesity." (PMID 38034250, 2023). "In the current study, the association between TCF7L2 rs7903146 variant and T2D remained significant after the adjustment for BMI, which is in agreement with previous reports that the rs7903146 variant confers T2D risk independently from BMI and obesity." (PMID 36674502, 2023). "This may be due to the that TCF7L2 also regulates adipose tissue via the Wnt pathway, and a potential association has been suggested between TCF7L2 and obesity development." (PMID 36155628, 2022). "TCF7L2 has been widely studied for its association with metabolic-related diseases, such as type 2 diabetes mellitus, obesity, metabolic syndrome, and cancers in various populations." (PMID 35341056, 2022). "Thus, the T2D‐associated TCF7L2 locus influences progression of islet autoimmunity, with differential effects given by autoantibody specificity and interaction of obesity or overweight status." (PMID 34612510, 2022).